WAC (WW domain containing adaptor with coiled-coil)
Description:
Acts as a linker between gene transcription and histone H2B monoubiquitination at 'Lys-120' (H2BK120ub1). Interacts with the RNA polymerase II transcriptional machinery via its WW domain and with RNF20-RNF40 via its coiled coil region, thereby linking and regulating H2BK120ub1 and gene transcription. Regulates the cell-cycle checkpoint activation in response to DNA damage. Positive regulator of amino acid starvation-induced autophagy. Also acts as a negative regulator of basal autophagy. Positively regulates MTOR activity by promoting, in an energy-dependent manner, the assembly of the TTT complex composed of TELO2, TTI1 and TTI2 and the RUVBL complex composed of RUVBL1 and RUVBL2 into the TTT-RUVBL complex. This leads to the dimerization of the mTORC1 complex and its subsequent activation. May negatively regulate the ubiquitin proteasome pathway.
Synonyms: Wwp4; FLJ31290; PRO1741; BM-016; MGC10753; DESSH
Tractability: PROTAC: ubiquitination databases record sites on it; its protein half-life has been measured.
Gene: Protein-coding gene on chromosome 10 (28,532,493 to 28,623,112, forward strand). Ensembl gene ENSG00000095787.
Subcellular location: Nucleus speckle; Nucleus
Subcellular location (Human Protein Atlas): Nucleoplasm; Centrosome
Pathways (Reactome):
Metabolism of proteins: E3 ubiquitin ligases ubiquitinate target proteins
Gene Ontology:
Molecular function: chromatin binding; protein binding; RNA polymerase II complex binding
Biological process: chromatin remodeling; DNA damage response; mitotic G1 DNA damage checkpoint signaling; negative regulation of proteasomal ubiquitin-dependent protein catabolic process; positive regulation of DNA-templated transcription; positive regulation of macroautophagy; positive regulation of TORC1 signaling; regulation of autophagy
Cellular component: nucleoplasm; nuclear speck; nucleus; spliceosomal complex
Genetic constraint (gnomAD): Loss-of-function variants: 10 observed, 68.39 expected, observed/expected ratio (o/e) 0.15, 90% interval 0.089 to 0.25. The upper end of that interval is the gene's LOEUF score, 0.25, which puts it in group 1 of 6, group 1 being the genes least tolerant of losing a copy. Missense variants: 700 observed, 767.71 expected, observed/expected ratio (o/e) 0.91, 90% interval 0.86 to 0.97. Synonymous variants: 294 observed, 280.45 expected, observed/expected ratio (o/e) 1.05, 90% interval 0.95 to 1.15.
Gene-disease validity (ClinGen):
ClinGen rates the evidence that WAC causes each of these diseases.
DeSanto-Shinawi syndrome (autosomal dominant): Definitive.
Homologues: Orthologues: chimpanzee WAC (98% identical), pig WAC (97% identical), dog WAC (96% identical), mouse Wac (95% identical), guinea pig WAC (94% identical), rat Wac (94% identical), macaque WAC (94% identical), rabbit WAC (92% identical), tropical clawed frog wac (81% identical), zebrafish waca (61% identical), Drosophila melanogaster wcy (29% identical), Caenorhabditis elegans wac-1.2 (6% identical).
Diseases named in the same sentence as WAC in open-access papers:
WAC is named in the same sentence as 38 diseases in open-access papers, as found by Europe PMC text mining. Sharing a sentence is not in itself a finding about the gene and the disease. The quoted sentences say what the papers report.
DeSanto-Shinawi syndrome (11 papers, 2021 to 2026). "The WAC gene has been primarily linked with DeSanto-Shinawi syndrome, a rare neurodevelopmental disorder." (PMID 42247028, 2026). "Desanto-Shinawi syndrome (DESSHS) is a rare autosomal dominant disorder caused by a loss of function variant or deletion of the WAC gene." (PMID 39493154, 2024). "WAC gene mutations are considered to be related to DeSanto–Shinawi syndrome, characterized by intellectual disability, behavioral disorders, and speech impairment." (PMID 38397281, 2024). "Dysfunction of the WW domain-containing adaptor with coiled-coil, WAC, gene underlies a rare autosomal dominant disorder, DeSanto–Shinawi syndrome (DESSH)." (PMID 37106788, 2023). "The WW domain containing adaptor with coiled-coil (WAC) gene is associated with DeSanto–Shinawi syndrome (DESSH)." (PMID 37106788, 2023). "Heterozygous truncating variations in WAC, as well as CNV deletions involving this gene, have been recently associated with the DeSanto-Shinawi syndrome, a rare neurodevelopmental disorder characterized by global developmental delay." (PMID 34324492, 2021). "A 1480 bp de novo deletion in WAC (Desanto-Shinawi syndrome, OMIM #616708 case 4203) was found in a male patient with seizures, hypotonia, developmental delay and nonfamilial features like low-set ears and brachycephaly." (PMID 34556655, 2021).
developmental delay (7 papers, 2020 to 2025). "The frequency of pathogenic WAC mutations is estimated to be very rare, with a frequency of 3/630 based on our cohort of subjects with developmental delay." (PMID 32214004, 2020).
Intellectual disability (6 papers, 2020 to 2025). "Lastly, the top differentially methylated CpG site at age 15 y was in the gene WAC, which has been linked to severe intellectual disability." (PMID 39277688, 2025). "The WAC gene has been recently associated with a recognizable neurodevelopmental disorder, the WAC-related intellectual disability (ID), also referred to as DeSanto–Shinawi syndrome (DESSH) (OMIM# 616708)." (PMID 32214004, 2020). "WAC (WW Domain Containing Adaptor With Coiled-Coil) mutations have been reported in only 20 individuals presenting a neurodevelopmental disorder characterized by intellectual disability, neonatal hypotonia, behavioral problems, and mildly dysmorphic features." (PMID 32214004, 2020).
autism spectrum disorder (3 papers, 2023 to 2025). A spectrum of developmental disorders that includes autism, and Asperger syndrome. "Moreover, WAC variants rank it as a high-confidence autism spectrum disorder risk gene." (PMID 37106788, 2023). "Dysfunction of the WAC gene underlies DESSH, as well as several comorbid neurological symptoms, including autism spectrum disorder, ADHD, and seizures." (PMID 37106788, 2023).
epilepsy (2 papers, 2020 to 2025). A brain disorder characterized by episodes of abnormally increased neuronal discharge resulting in transient episodes of sensory or motor neurological dysfunction, or psychic dysfunction. "Seizures or epilepsy have been reported in only four patients with WAC point mutations." (PMID 32214004, 2020). "Similarly, three of the reported individuals with epilepsy carrying a LoF WAC mutation had a severe phenotype, which included significant motor and language delay, behavioral problems, sleep disturbances, and gastrointestinal problems." (PMID 32214004, 2020). "Although other genetic factors could be involved in the electrical status epileptic during sleep pattern in the case we report, the presence of epilepsy and/or electrical status epileptic during sleep might reflect the severe end of the clinical spectrum caused by WAC haploinsufficiency." (PMID 32214004, 2020).
colorectal cancer (1 paper, 2021). A primary or metastatic malignant neoplasm that affects the colon or rectum. "The WAC gene has been mutated in murine colorectal cancer mutagenesis screens, and that reduction in WAC expression reduces cell growth." (PMID 34512726, 2021). "Among them, HNRNPH1 and WAC, targeted by hsa-miR-4772-5p, have been described in previous colorectal cancer studies." (PMID 34512726, 2021).
congenital heart disease (1 paper, 2024). A heart disease that is present at birth. "Similarly, variable congenital heart disease was documented in previous case reports of DESSHS especially those with 10p12.1 microdeletion including the WAC gene." (PMID 39493154, 2024).
Encephalopathy (1 paper, 2020). Encephalopathy is a term that means brain disease, damage, or malfunction. "In conclusion, here we report three novel individuals with WAC LoF mutations, one of them presenting encephalopathy related to electrical status epilepticus during sleep." (PMID 32214004, 2020).
focal epilepsy (1 paper, 2020). A seizure caused by a localized disorder. "In this study, we report a LoF WAC mutation in a subject with focal epilepsy (patient 3)." (PMID 32214004, 2020).
glioma (1 paper, 2022). A benign or malignant brain and spinal cord tumor that arises from glial cells (astrocytes, oligodendrocytes, ependymal cells). "The results indicated that LINC0090, MIR155JG and CRNDE were significantly upregulated in glioma samples, and TTC28.AS1and WAC.AS1 were downregulated." (PMID 35237509, 2022). "SNHG18, NEAT1, LINC00339) and low expression of four lncRNAs (DICER1.AS1, NNT.AS1, WAC.AS1, TTC28.AS1 were with poor prognosis in glioma." (PMID 35237509, 2022).
heart malformations (1 paper, 2021). "Furthermore, in two non-consanguineous unrelated individuals with heart malformations, among other disorders, microdeletions at 10p11.23-p12.1 (overlapping ARMC4, MPP7, BAMBI and WAC) were identified." (PMID 34324492, 2021).
lung squamous cell carcinoma (1 paper, 2025). "Analysis of WAC protein levels revealed that these were significantly upregulated in most cancer types (five out of eight; P‐value < 0.05), including lung squamous cell carcinoma (LUSC) and ovarian serous cystadenocarcinoma (OV)." (PMID 40653822, 2025).
microcephaly (1 paper, 2025). A congenital or acquired developmental disorder in which the circumference of the head is smaller than normal for the person's age and sex. "Case UniPD_0148 with the pathogenic WAC variant p.(Ser125Ter) showed microcephaly, which has been inconsistently reported in other WAC patients." (PMID 40019509, 2025). "Conversely, three cases with pathogenic variants in CHD8, WAC, and MED12 exhibited microcephaly, despite these genes typically not being associated with reduced head size." (PMID 40019509, 2025).
osteoporosis (1 paper, 2025). A condition of reduced bone mass, with decreased cortical thickness and a decrease in the number and size of the trabeculae of cancellous bone (but normal chemical composition), resulting in increased fracture incidence. "Our findings position WAC as a critical factor in MSCs, linking its deficiency to osteoporosis pathogenesis and underscoring its pivotal role in promoting osteogenic differentiation." (PMID 39555688, 2025). "We revealed a WAC deficiency in osteoporosis and uncovered the role of WAC in promoting MSC osteogenesis via PINK1‐mediated mitophagy." (PMID 39555688, 2025). "In this study, we illuminate the downregulation of WAC expression in osteoporosis and its pivotal influence on the osteogenic differentiation of MSCs in vitro." (PMID 39555688, 2025). "Our findings propose that WAC positively modulates the osteogenic process of MSCs, both in vivo and in vitro, making it a promising target for osteoporosis and bone defect repair." (PMID 39555688, 2025). "Here, the data reveal that the levels of WAC are diminished in both osteoporosis patients and osteoporosis mouse models." (PMID 39555688, 2025). "In addition, we collected MSCs from osteoporosis patients (OP) and found that both the mRNA and protein levels of WAC were down‐regulated in OP compared to non‐OP samples." (PMID 39555688, 2025). "The study elucidates the mechanism by which WAC modulates MSC osteogenesis, binds to PINK1 to protect it from ubiquitination, and identifies potential therapeutic targets for osteoporosis and bone defect repair." (PMID 39555688, 2025). "Our investigation extended to evaluate the potential of WAC and PINK1 as novel targets for the treatment of osteoporosis and bone repair." (PMID 39555688, 2025). "This intervention demonstrated a reversal of impaired bone defect repair in WAC‐CKO mice, emphasizing the potential of WAC and PINK1 as key targets in both osteoporosis treatment and bone restoration." (PMID 39555688, 2025). "Together, these data indicated that WAC deletion leads to impaired bone formation in vivo and WAC and PINK1 are effective targets for the treatment of osteoporosis and bone defects." (PMID 39555688, 2025). "Together, these data suggest an important role of WAC in MSC osteogenesis and osteoporosis." (PMID 39555688, 2025). "In order to explore the potential of targeting WAC and PINK1 to mitigate the progression of osteoporosis and promote bone formation, we designed the bone‐targeting recombinant adeno‐associated virus 9 (rAAV9) for the specific overexpression of WAC and PINK1 in bone tissue." (PMID 39555688, 2025).
pancreatic ductal adenocarcinoma (1 paper, 2025). An infiltrating adenocarcinoma that arises from the epithelial cells of the pancreas. "In contrast, WAC protein levels were reduced in pancreatic ductal adenocarcinoma, suggesting that its regulation may be tumor‐type specific." (PMID 40653822, 2025).
neurodevelopmental disorder (4 papers, 2020 to 2026). A behavioral and cognitive disorder with onset during the developmental period that involves impaired or aberrant development of intellectual, motor, or social functions. "The variable degree of ID associated with behavioral problems as well as the non-specific/coarse facial appearance found in patients with WAC mutations have significant similarities with other neurodevelopmental disorders." (PMID 32214004, 2020).
cancer (3 papers, 2021 to 2025). A tumor composed of atypical neoplastic, often pleomorphic cells that invade other tissues. "We first characterized cancer‐type‐specific variations in the expression of WAC, mTORC1, and R2TP‐TTT components, followed by an analysis of potential co‐expression patterns." (PMID 40653822, 2025). "Transcriptomic and proteomic analysis shows that WAC, mTOR, R2TP, and TTT are co‐expressed across several human cancers, supporting that WAC is part of a functional pathway with mTOR, R2TP, and TTT." (PMID 40653822, 2025). "In addition, we also detected associations between WAC and components of R2TP (three to four out of 10 cancer types) and TTT (2 out of 10 cancer types), which is consistent with the involvement of WAC, R2TP, and TTT in the same pathway." (PMID 40653822, 2025). "WAC expression was also correlated with that of RPAP3 and PIH1D1 (in three out of 10 cancer types), components of R2TP, and we also found some correlation with TTI2." (PMID 40653822, 2025). "Consistent with the literature, the results of the present study showed fusion of the FGFR2 gene with nine different partners, namely, TACC2, BICC1, BTBD16, WAC, HFM1, HOOK1, INPP5F, C10orf90, and WDR11, in five different types of cancer." (PMID 35342406, 2022). "All integrations in the cancer samples occurred within or near the cancer-related genes PVT1, WAC and miR-205." (PMID 34175494, 2021). "Together, all these results reveal that the expression of WAC is correlated with components of the R2TP, TTT, and mTORC1 complexes in several tumors, reinforcing the notion that WAC and the R2TP‐TTT chaperone complexes functionally cooperate to regulate mTORC1 in cancer." (PMID 40653822, 2025). "Our transcriptomic and proteomic analyses supported a relevant role of WAC in the R2TP‐TTT pathway by revealing that WAC expression and protein levels are correlated with those of R2TP and TTT in several tumors, suggesting that they are part of a functional pathway that contributes to some cancers." (PMID 40653822, 2025). "The interaction of WAC with mTORC1 and with the R2TP‐TTT chaperone suggests that there should also be functional links among these proteins that could reflect in a correlated transcription and/or protein expression in some cancer contexts." (PMID 40653822, 2025).
Tumor (3 papers, 2016 to 2025). "We observed that WAC and components of mTORC1, R2TP, and TTT complexes are broadly expressed at both mRNA and protein levels across multiple tumor types." (PMID 40653822, 2025).
infection (2 papers, 2016 to 2026). The state of being infected such as from the introduction of a foreign agent such as serum, vaccine, antigenic substance or organism. "These kinetics also correlate well with the stimulation of inflammatory gene expression by both WAC and WA314 after 1.5 h of infection and with suppression of gene expression by WA314 after 6 h of infection." (PMID 41277869, 2026). "Western blot analysis revealed that the combined H3K9me3/H3S10ph modification increased in parallel to the H3S10ph modification in WAC-treated cells and was strongly inhibited, like the H3S10ph modification, in the WA314-treated cells from 3 to 6 h of infection." (PMID 41277869, 2026).
WAC also shares sentences with these, for which no sentence is quoted: autism (2 papers); behavioral disorders (1); bone metabolism disorders (1); breast carcinoma (1); central nervous system disorder (1); cholangiocarcinoma (1); gastric cancer (1); Hydrocephalus (1); learning disabilities (1); leprosy (1); neurological disorders (1); ovarian serous cystadenocarcinoma (1); rectum adenocarcinoma (1); sarcoma (1); Seizure (1); status epilepticus (1); Thrombocytopenia (1); thymoma (1); uterine corpus endometrial carcinoma (1).